EGFR (epidermal growth factor receptor)
Diseases named in the same sentence as EGFR in open-access papers (continued):
Sharing a sentence is not in itself a finding about the gene and the disease.
cancer (continued). "With the importance of EGFR expression in cancer being evident, several approaches to inhibit EGFR have been undertaken." (PMID 35455447, 2022). "Blocking the extracellular domain of EGFR using an EGF ligand or downregulation of the EGFR mRNA with ASO anti-EGFR reduced the B-ASO uptake by more than 50% in the tested cancer cell lines." (PMID 36499115, 2022). "Compared with free ZnPc, all the conjugates exhibited high specific affinity to EGFR-overexpressing cancer cells due to the presence of erlotinib, maintaining at the same time the high phototoxicity of the ZnPc core." (PMID 35213974, 2022). "Combining sorafenib with panitumumab significantly down regulated the expression of each of VEGFR and EGFR in HepG2 cancer treated cells." (PMID 36284117, 2022). "The immunoblotting and qPCR results further signified that 6b inhibited EGFR in tissue samples and consequently altered the downstream pathways mediated by EGFR, leading to a reduction in cancer growth." (PMID 36080307, 2022). "EGFR mutations can upregulate CD73 expression, increase Treg numbers, and stimulate conversion of ATP into immunosuppressive adenosine, contributing to cancer progression and metastasis." (PMID 35742933, 2022). "Nakata and colleagues proposed that targeting the Akt/β-catenin pathway can enhance the therapeutic efficacy of EGFR tyrosine kinase inhibitors in drug-resistant cancers, suggesting the crucial role of β-catenin in cancer progression." (PMID 35744950, 2022). "Human epidermal growth factor receptor 2 (HER2) is an epithelial growth factor receptor (EGFR)-related tyrosine kinase that is found to be overexpressed in many malignant tumors such as breast, ovarian, and gastric cancers." (PMID 36274167, 2022). "The overexpression of epidermal growth factor receptor (EGFR) can be observed in different types of cancer." (PMID 36335233, 2022). "The tests were performed on cancer cells with different levels of expression of EGFR (A431, U87-MG, HTC-116, HeLa, MG-63, MCF-7) and normal cells (HEK-293, CCD-841-CoN, MEF-WT, h-FOB 1.19, NHDF) as well as on human macrophages (three independent donors)." (PMID 36499115, 2022). "Resistance to EGFR-TKIs induces a cancer stem cell phenotype while suppression of cancer stem cell properties ameliorates EGFR-TKIs resistance." (PMID 35301287, 2022). "Despite great therapeutic successes, the clinical application of three generations of EGFR inhibitors inevitably leads to acquired drug resistances, which has presented a new challenge of treating cancers." (PMID 35589670, 2022). "Given that this receptor is commonly dysregulated in cancer, there has been enormous interest in studying EGFR-driven signalling cascades." (PMID 36400876, 2022). "In cancer cells, inhibition of EGFR with TKIs or monoclonal antibodies can result in decreased cell movement, differentiation, and proliferation." (PMID 35978801, 2022). "Previous studies have shown that overexpression of EGFR promotes chemoresistance in cancer cells, and that EGFR-mediated activation of the MAPK and PI3K pathways can be observed following chemotherapy exposure." (PMID 35289315, 2022). "ANXA2 at the cancer cell membrane surface interacts with EGFR and it is critical for the regulation of downstream signalling." (PMID 36224238, 2022). "The lower expression of EGFR apparently led to killing the cancer cells, thereby decreasing the viability of MCF-7 cells as reflected in the MTT assay." (PMID 36412852, 2022). "Therapies targeting the EGFR signaling, such as small-molecule tyrosine kinase inhibitors (TKIs), have been used to treat a variety of cancers." (PMID 36471329, 2022). "Next, to precisely quantify the accumulation of HX103 in living cells, we turned to FACS analysis in cancer cells with different forms of EGFR." (PMID 36376325, 2022). "EGFR is overexpressed in various epithelial tumors, and its abnormal activation is closely correlated with cancer occurrence and development." (PMID 36551506, 2022).
cancer (continued). "Being a multifactorial process, acquisition of paclitaxel resistance resulted in sustained dysregulation of several cancer-related pathways, including upregulation of EGFR." (PMID 36139693, 2022). "ING5 suppresses aggressive phenotypes of various cancer cells via EGFR/PI3K/Akt, IL-6/STAT3, Akt/NF-κB/NF-κB/MMP-9 or IL-6/CXCL12 pathway." (PMID 36425530, 2022). "The epidermal growth factor receptor (EGFR) plays a pivotal role in the proliferation and metastatization of cancer cells." (PMID 35213974, 2022). "While less well established, ERβ dynamically communicates with major matrix components, including PGs and epidermal growth factor receptor (EGFR) to stimulate cancer cell behavior, epithelial-to-mesenchymal transition (EMT) and stem-like characteristics." (PMID 35719919, 2022). "Some evidence suggests that EGFR-TKI resistance works through an integrin-mediated pathway, and FAK is involved in the increase in resistance of cancer cells to EGFR-TKI." (PMID 36407100, 2022). "Epidermal growth factor receptor inhibitors (EGFRIs) and tyrosine kinase inhibitors (TKIs) are key drugs in targeted cancer therapy." (PMID 36204127, 2022). "The evidence above indicates the mechanisms related to ARID1A-KD through which a better response to ICIs occurs, and further verification was performed using EGFR-mutant LUAD cohorts from our cancer center and TCGA." (PMID 36229854, 2022). "In this report, we provide the first evidence that DARPP-32 overexpression in EGFR-mutated LUAD promotes ERBB3-mediated oncogenic signaling to drive EGFR TKI therapy-refractory cancer progression." (PMID 34675407, 2022). "As a result, NEDD4L was negatively correlated to EGFR mRNA and protein levels in cancer tissues in the TCGA_LUAD dataset." (PMID 35090513, 2022). "SPION@bPEI nanoparticles were further conjugated with Erbitux (Erb), which is an anti-EGFR antibody for targeting EGFR-overexpressing cancer cell lines." (PMID 35116215, 2022). "PI3K/ATK/mTOR and Ras/MAPK pathway activation are involved with constitutive PD-L1 regulation in many cancers; loss of PTEN or mutations in PIK3CA lead to PI3K/ATK/mTOR pathway activation, while mutations in EGFR or Ras lead to Ras/MAPK pathway activation." (PMID 35164673, 2022). "Eventually, this process can result in tumorigenesis and cancer progression, thereby making EGFR one of the main anticancer targets." (PMID 36096856, 2022). "Metabolic reprogramming is inevitably triggered by constitutively active EGFR signaling pathways, empowering cancer initiation and progression." (PMID 35203491, 2022). "We employed a proportional odds model to identify significant drug targets and the corresponding compounds that increased the likelihood of stable disease versus progressive disease in cancer patients that had the EGFR WT gene." (PMID 36230688, 2022). "Recently, an amplified electrochemical DPV biosensor was reported, based on an aptamer/antibody (Apt/Ab) sandwich format, for the detection of epidermal growth factor receptor (EGFR), a cancer biomarker." (PMID 35457828, 2022). "Epidermal growth factor receptor (EGFR) is widely recognized because it is of great importance in many kinds of cancers." (PMID 36267410, 2022). "We studied ctDNA and tissue biopsy to investigate EGFR, KRAS, NRAS, and BRAF mutations from 199 cancer patients between January 2016 and March 2021." (PMID 36497340, 2022). "Epidermal growth factor (EGF) signalling regulates normal epithelial and other cell growth, with EGF receptor (EGFR) overexpression reported in many cancers." (PMID 35612280, 2022). "The results indicate that this herbal extract inhibits the cell proliferation and migration, and induces apoptosis of both cancer cell lines via the inhibition of EGFR signalling pathway." (PMID 34882994, 2022). "RAS, PI3K, and EGFR, which are involved in both glycolysis pathways and cancer pathway, were significantly upregulated." (PMID 36090994, 2022).
cancer (continued). "EGFR is a potent oncogene frequently overexpressed in a variety of cancers and is already a well-known therapeutic target in cancer therapy." (PMID 35421091, 2022). "EGF efficiently addressed the nanoparticles against EGFR-overexpressing cancer cells, showing superior phototoxicity when compared to free photosensitizers." (PMID 35213974, 2022). "Recent studies established that EGFR can be used as a prognostic and predictive molecular marker for nCT in various cancers." (PMID 36569844, 2022). "Our study identified that EGFR L858R neoantigen had the potential to generate cancer vaccines in NSCLC patients with HLA A*33:03." (PMID 36505399, 2022). "In a rescue experiment, more cytotoxicity was observed in EGFR-CAR T cells when ICAM-1 was overexpressed on IFNγR1-KO cancer cells." (PMID 36085295, 2022). "Targeting of these oncogenes for cancer therapy is therefore of particular interest, and their specific inhibitors (e.g., erlotinib, vemurafenib, and trametinib, inhibitors of EGFR, BRaf, and MEK, respectively) are currently in clinical use10." (PMID 35831322, 2022). "In this study, the epidermal growth factor receptor (EGFR) exon number 19 was selected as the target for cancer detection." (PMID 35591635, 2022). "Silibinin, taspine and resveratrol reportedly bind to EGFR to block its activation and subsequently dampen its downstream signaling pathways in cancer cells." (PMID 35269825, 2022). "Our first example is the epidermal growth factor receptor (EGFR), a signalling membrane receptor involved in several types of cancers." (PMID 36291736, 2022). "Several members of the Epidermal Growth Factor Receptor (EGFR) family, have been identified in the nucleus and nucleolus of many cancer cells, but their function in these compartments remains unexplored." (PMID 35255831, 2022). "The majority of EpCAM+EGFR+ events detected in blood samples of cancer patients were doublets of PBMCs, red blood cells or a combination thereof." (PMID 36613466, 2022). "The epidermal growth factor receptor (EGFR), also known as proto-oncogene c-ErbB-1, receptor tyrosine-protein kinase erbB-1 (Her1 in humans), represents another common target for anti-cancer immunotherapeutic." (PMID 36498915, 2022). "Aberrant EGFR expression and activation play an important role in the development and progression of various cancers." (PMID 36556437, 2022). "In the present study, we decided to further analyze the effect of DHRS7 knockdown on EGFR because of its importance in cell signaling and cancer treatment." (PMID 35804847, 2022). "Human epidermal growth factor receptor 2 (HER2), which belongs to the epidermal growth factor receptor (EGFR) superfamily, is a protein involved in one of the most studied signal transduction pathways in cancer." (PMID 35945910, 2022). "Proverbially, overexpression of the epidermal growth factor receptor (EGFR) was connected with various cancers." (PMID 36263174, 2022). "Lactadherin was also used as an anchor for cancer-targeting moiety—single chain variable fragments (scFv) with an affinity to human epidermal growth factor receptor (EGFR) 2 overexpressed in breast cancer cells." (PMID 36290464, 2022). "We show that ADAM17 sheds heparin-binding EGF (HB-EGF) and amphiregulin (AREG) from the cancer cell surface, leading to EGFR activation in macrophages." (PMID 35998057, 2022). "REST target genes upregulated in ER- or TNBCs include MYC, LIF, and EGFR which play significant roles in cancer progression, cell proliferation and endocrine resistance." (PMID 35177031, 2022). "EGF is one of the most abundant growth factors, promoting EMT during metastasis by binding to EGFR on the plasma membrane of cancer cells." (PMID 35884900, 2022).
cancer (continued). "The pathway scores of cell proliferation, cellular growth factor, cellular differentiation, choline cancer metabolism, and carbon cancer metabolism were shown to have functional statuses with the EGFR." (PMID 36005485, 2022). "Each compound was docked with each cancer target protein, namely EGFR, NF-kB and progesterone receptor." (PMID 36144225, 2022). "The eradication of EGFR protein from cancer cells provides a promising strategy for overcoming drug resistance." (PMID 35840984, 2022). "When EGFR activity in cancer cells is inhibited, phosphorylation of STAT3 is diminished, thereby inhibiting cancer cell proliferation and improving resistance to the drug." (PMID 36291659, 2022). "The two patients who had targeted therapy during their course of cancer treatment received inhibitors of the epidermal growth factor receptor (EGFR)/human epidermal growth factor receptor 2 (HER2) pathway." (PMID 35572995, 2022). "The EGFR is a well-known oncogene involved in the onset and progression of different types of cancer." (PMID 35954311, 2022). "Although, recent advancements in therapeutics have made it possible to overcome EGFR-TKIs resistant cancer types, however, the adverse effects, unmapped targets and cellular responses to the available drugs require further investigation." (PMID 35281907, 2022). "EGFR inhibitors have beneficial effects against cell proliferation and progression in a wide variety of cancer types." (PMID 35421091, 2022). "Highly expressed in various solid cancers, including breast, colon, lung and PC, the EGFR promotes rapid mitosis and stamina in cancer cells." (PMID 36106025, 2022). "Although EGFR inhibitors have to date only been approved for cancer treatment, other research does suggest that they have potential benefit for inflammatory lung diseases such as COPD." (PMID 35967296, 2022). "This study provides novel insights into the USP6NL/EGFR axis that suppresses anticancer therapeutic responses, induces cancer invasiveness, and facilitates reduced sensitivity to TMZ treatment in GBM in an autolysosome-dependent manner." (PMID 35884836, 2022). "The increased expression of EGFR in some epithelial tumors can be used as a receptor target for cancer drug delivery system." (PMID 34973131, 2022). "Epidermal growth factor receptor (EGFR) pathways are mostly observed to be dysregulated in human cancers, attracting researchers for targeted anticancer therapy." (PMID 36518665, 2022). "Each cancer cell line was labeled with fluorescein‐conjugated antibodies against EGFR (α‐EGFR‐FL), HER2 (α‐HER2‐FL), CD38 (α‐CD38‐FL) and were cocultured with FL‐CAR T cells." (PMID 35146940, 2022). "The pathways characterizing the Intestinal GC, in addition to other cancer-related pathways, were involved in cell cycle regulation and response to growth factors and hormones (EGFR, estradiol, progesterone)." (PMID 36230884, 2022). "The focus is on the successes and limitations of therapies targeting the activation of EGFR versus those that exploit the cytotoxic T cells and innate immune cells to target EGFR-expressing cancer cells." (PMID 36185288, 2022). "In this study, we found that the expression of UTX in cancer tissues of patients with NSCLC was significantly higher than that in paracancerous tissues, and positively associated with EGFR phosphorylation levels." (PMID 34661759, 2022). "EGFR is overexpressed in various cancers, such as colorectal cancer (CRC), lung cancer, breast cancer, glioblastoma, and head and neck squamous cell carcinoma." (PMID 35628495, 2022). "Pyrimidines have been explored and are widely used heterocycles for determining their activity against various types of cancer, but most reported articles suggest the pyrimidine’s potential in inhibiting EGFR in different types of cancers." (PMID 35769445, 2022).
cancer (continued). "This demonstrated that combinatorial treatments with anti-PD-1 or anti-PD-L1 inhibitors with targeted therapy substantially prolonged the PFS of cancer patients with the EGFR WT gene." (PMID 36230688, 2022). "The Cr(VI)‐induced ALDH1A1 maintains self‐renewal of the CrT/TIC subpopulation and promotes expression and secretion of EGF from CrT/TICs to activate EGFR signalling of differentiated cancer cells, promoting LUSC tumourigenesis." (PMID 36504325, 2022). "We recapitulate the chemistry of the sensitizers and their modes of action in PDT, and summarize the advantages and pitfalls of different targeting moieties, highlighting future perspectives for EGFR-targeted photodynamic treatment of cancer." (PMID 35213974, 2022). "The resulting derivatives were tested for the activity of HDAC and protein kinase inhibition in various biochemical assays and EGFR or HER2 overexpressing cancer cell lines were further used to determine the cytotoxicity of the chimeric derivatives." (PMID 35408693, 2022). "Caco2 cells overexpressing the epidermal growth factor receptor (EGFR) showed significantly greater anti-cancer activity than that of cells from the HCT-116 cell line." (PMID 35455247, 2022). "Genes placed in the second cluster have variable correlations with EGFR dependency across the cancer cell lines from both clusters, and thus they should be studied separately for each cancer type." (PMID 36361596, 2022). "Gefitinib is quite popularly used for cancer treatment that targets the epidermal growth factor receptor (EGFR)." (PMID 36106139, 2022). "The plasma membrane-receptors, such as integrin αvβ3, estrogen receptor (ER), and epidermal growth factor receptor (EGFR), drive cancer cell growth." (PMID 35705962, 2022). "In recent years, studies on the formation of EGFR heterodimers with family partners, or other RTKs, respectively to promote cancer or drug resistance through multiple pathways, including PI3K/AKT/mTOR, Ras/MEK/ERK, and JAK/STAT have been conducted." (PMID 35681787, 2022). "For 536 cancer cell lines, we first estimate drug sensitivity-specific gene networks under varying EGFR TKI sensitivity of cell lines." (PMID 35584089, 2022). "Our novel informatic pipeline identified six significant drug targets and thirteen specific compounds for EGFR WT cancer patients." (PMID 36230688, 2022). "For first-line and second-line chemotherapy combined with bevacizumab, cetuximab, BRAF and epidermal growth factor receptor (EGFR) inhibitors, and immunotherapy, it can effectively prolong the median survival of patients with advanced cancer." (PMID 36203415, 2022). "In the following paragraphs, we describe the main steps in the characteristic cancer-immunity cycle of patients with EGFR-mutant NSCLC to explore the potential mechanism underlying the poor immunotherapy response." (PMID 35935943, 2022). "Over the last decade, the tumorigenic properties of AnxA6 have been amply described in several cancer types, as well as in the resistance of TNBCs to EGFR-TKIs." (PMID 36230969, 2022). "In the therapy of cancer patients through EGFR inhibition, it has been reported that the regulation of the EGFR downstream proteins is important to determine the clinical response." (PMID 35572726, 2022). "Small-molecule tyrosine kinase inhibitors (TKIs) and monoclonal antibodies (mAbs) are two different therapeutic methods used to target EGFR in diverse human cancers." (PMID 35455247, 2022). "In previous publications, we showed that the siRNA in this complex is stabilised by the tight interaction with protamine, internalises into EGFR-positive cells and exerts therapeutic anti-cancer activity in vitro and in vivo." (PMID 35220407, 2022).